FHIT (fragile histidine triad diadenosine triphosphatase)
Description:
Possesses dinucleoside triphosphate hydrolase activity. Cleaves P(1)-P(3)-bis(5'-adenosyl) triphosphate (Ap3A) to yield AMP and ADP. Can also hydrolyze P(1)-P(4)-bis(5'-adenosyl) tetraphosphate (Ap4A), but has extremely low activity with ATP. Exhibits adenylylsulfatase activity, hydrolyzing adenosine 5'-phosphosulfate to yield AMP and sulfate. Exhibits adenosine 5'-monophosphoramidase activity, hydrolyzing purine nucleotide phosphoramidates with a single phosphate group such as adenosine 5'monophosphoramidate (AMP-NH2) to yield AMP and NH2. Exhibits adenylylsulfate-ammonia adenylyltransferase, catalyzing the ammonolysis of adenosine 5'-phosphosulfate resulting in the formation of adenosine 5'-phosphoramidate. Also catalyzes the ammonolysis of adenosine 5-phosphorofluoridate and diadenosine triphosphate. Modulates transcriptional activation by CTNNB1 and thereby contributes to regulate the expression of genes essential for cell proliferation and survival, such as CCND1 and BIRC5. Plays a role in the induction of apoptosis via SRC and AKT1 signaling pathways. Induction of apoptosis depends on the ability of FHIT to bind P(1)-P(3)-bis(5'-adenosyl) triphosphate or related compounds, but does not require its catalytic activity, it may in part come from the mitochondrial form, which sensitizes the low-affinity Ca(2+) transporters, enhancing mitochondrial calcium uptake. Functions as a tumor suppressor (By similarity).
Synonyms: AP3Aase; FRA3B
Tractability: Small molecule: a structure with a bound ligand is known; a high-quality ligand is known; it has a binding pocket of medium quality. Antibody: its Gene Ontology location is reachable by antibodies, with high confidence; the Human Protein Atlas places it where antibodies can reach. PROTAC: a small molecule that binds it is known.
Target class: Enzyme; Hydrolase
Gene: Protein-coding gene on chromosome 3 (59,747,277 to 61,251,459, reverse strand). Ensembl gene ENSG00000189283.
Subcellular location: Cytoplasm; Mitochondrion; Nucleus
Subcellular location (Human Protein Atlas): Nucleoli fibrillar center; Plasma membrane
Gene Ontology:
Molecular function: adenosine 5'-monophosphoramidase activity; adenylylsulfatase activity; adenylylsulfate-ammonia adenylyltransferase activity; bis(5'-adenosyl)-triphosphatase activity; identical protein binding; protein binding; ubiquitin protein ligase binding; catalytic activity
Biological process: diadenosine triphosphate catabolic process; negative regulation of proteasomal ubiquitin-dependent protein catabolic process; purine nucleotide metabolic process
Cellular component: cytoplasm; cytosol; mitochondrion; nucleus
Genetic constraint (gnomAD): Loss-of-function variants: 18 observed, 16.93 expected, observed/expected ratio (o/e) 1.06, 90% interval 0.73 to 1.57. The upper end of that interval is the gene's LOEUF score, 1.57, which puts it in group 6 of 6, group 1 being the genes least tolerant of losing a copy. Missense variants: 245 observed, 193.3 expected, observed/expected ratio (o/e) 1.27, 90% interval 1.14 to 1.41. Synonymous variants: 81 observed, 72.87 expected, observed/expected ratio (o/e) 1.11, 90% interval 0.93 to 1.34.
Cancer hallmarks: genome instability and mutations (suppresses); invasion and metastasis (suppresses)
Homologues: Orthologues: chimpanzee FHIT (99% identical), macaque FHIT (96% identical), dog FHIT (93% identical), guinea pig FHIT (92% identical), mouse Fhit (91% identical), rat Fhit (90% identical), zebrafish fhit (77% identical), tropical clawed frog fhit (76% identical), pig FHIT (65% identical). Paralogues in human: HINT1 (19% identical), HINT2 (18% identical).
Diseases named in the same sentence as FHIT in open-access papers:
FHIT is named in the same sentence as 152 diseases in open-access papers, as found by Europe PMC text mining. Sharing a sentence is not in itself a finding about the gene and the disease. The quoted sentences say what the papers report.
lung carcinoma (71 papers, 2003 to 2025). "This study highlights that GSK3β, as well as the HRR pathway, is a potential actionable target in FHIT-deficient lung cancer and provides the first candidate for FHIT-targeting synthetic lethal therapy for smokers with lung cancer." (PMID 39762409, 2025). "FHIT-deficient lung cancer cells were more sensitive to the GSK3β inhibitor than FHIT-proficient cells were in all three FHIT-isogenic pairs tested." (PMID 39762409, 2025). "We further investigated the effects of the GSK3β inhibitor on the HRR and NHEJ signaling pathways in FHIT-wild-type and FHIT-deficient lung cancer cells." (PMID 39762409, 2025). "We used the ATR inhibitor VE-821 and the DNA-PK inhibitor NU-7441 as inhibitors of HRR and NHEJ, respectively, and analyzed their synthetic lethal effects on FHIT-deficient lung cancer cells." (PMID 39762409, 2025). "We observed that geldanamycin partially induced synthetic lethality with FHIT loss in lung cancer cells, accompanied by the downregulation of BRCA1 and RAD51 levels." (PMID 39762409, 2025). "We also tested the effects of geldanamycin, an inhibitor of HSP90 that has been shown to mediate FHIT-regulated HRR protein stability, on synthetic lethality in FHIT-deficient lung cancer cells." (PMID 39762409, 2025). "We showed that a GSK3β inhibitor selectively inhibited FHIT-deficient lung cancer by inhibiting the ATR/BRCA1/RAD51 signaling axis and BRCA1/RAD51 transcription, leading to the inhibition of HRR and genotoxic cell death." (PMID 39762409, 2025). "The findings of this study suggest that the GSK3β and HRR pathways are potential drug targets in lung cancer patients with FHIT loss." (PMID 39762409, 2025). "As such, little progress has been made in exploiting the loss of FHIT for lung cancer targeted therapy development." (PMID 39762409, 2025). "In this study, we employed a synthetic lethal drug screening approach to target lung cancer with FHIT loss and identified GSK3β as a synthetic lethal partner of FHIT in lung cancer cells." (PMID 39762409, 2025). "Our study provides strong evidence that inhibiting the GSK3β and HRR pathways is a promising strategy for targeting FHIT loss in smokers with lung cancer." (PMID 39762409, 2025). "Here, we report that inhibitors of glycogen synthase kinase 3 beta (GSK3β) and the homologous recombination DNA repair (HRR) pathway are synthetic lethal with FHIT loss in lung cancer." (PMID 39762409, 2025). "X and cleaved-caspase 3 levels were largely increased in FHIT-deficient lung cancer cells treated with CHIR99021." (PMID 39762409, 2025). "FHIT loss is frequently observed in lung cancer, making it an important biomarker for the development of targeted therapy for lung cancer." (PMID 39762409, 2025). "Annexin-V staining and PARP Western blots also revealed that the GSK3β inhibitor CHIR99021 significantly increased apoptosis in FHIT-deficient lung cancer cells." (PMID 39762409, 2025). "This study revealed that the GSK3β and HRR pathways are new targets for developing FHIT loss-associated targeted therapies for lung cancer in smokers." (PMID 39762409, 2025). "This information will largely facilitate the elucidation of the functions of FHIT in tumor suppression in lung cancer and promote the identification of new druggable targets associated with FHIT loss." (PMID 39762409, 2025). "In this study, we found that GSK3β inhibition is synthetic lethal with FHIT loss in lung cancer cells." (PMID 39762409, 2025). "They tested drugs on lung cancer cells and discovered that blocking GSK3β (an enzyme involved in various cell processes) killed FHIT-deficient cells." (PMID 39762409, 2025). "Analysis of tumor samples revealed that BRCA1 and RAD51 levels were elevated in FHIT-deficient lung cancer, and CHIR99021 treatment reduced their protein levels." (PMID 39762409, 2025). "All FHIT-deficient lung cancer cells presented increased expression levels of BRCA1 and RAD51 and increased levels of phosphorylated DNA-PKcs." (PMID 39762409, 2025).
lung carcinoma (continued). "Pharmacological inhibition or siRNA depletion of GSK3β selectively suppressed the growth of FHIT-deficient lung cancer tumors in vitro and in animal models." (PMID 39762409, 2025). "FHIT hypermethylation was also associated with an increased risk of lung cancer and a worse overall survival from the disease." (PMID 34368151, 2021). "This is a well known tumor suppressor gene whose expression has been shown to exhibit an inverse correlation with HMGA2 in lung cancer, where FHIT enhances the expression of miR-30c and causes HMGA2 repression." (PMID 28423547, 2017). "To address this we performed ribosome profiling of Fhit-deficient H1299 lung cancer cells carrying an inducible FHIT transgene and a matching cell line carrying empty vector." (PMID 29282095, 2017). "As expected, a significant association was found between FHIT methylation and NSCLC in meta-analysis (OR = 3.43), indicating the existence of a strong association between FHIT promoter methylation and lung cancer." (PMID 28036263, 2017). "The cumulative evidence in our study is now conclusive that the FHIT gene promoter hypermethylation is associated with lung cancer formation and development, male gender, smoking behavior, and worse survival." (PMID 26796853, 2016). "By searching Pubmed, CNKI and Wanfang, the open published articles related to FHIT gene promoter methylation and lung carcinoma risk were collected." (PMID 24667261, 2014). "Homozygous deletions leading to total loss of specific FHIT exons, and thus total loss of FHIT protein, has been demonstrated in primary cancers such as esophageal, gastric and lung carcinomas." (PMID 24901304, 2014). "The FHIT gene located in chromosome 3p14.2 undergoes frequent allele loss of heterogeneity (LOH) or homozygous deletions in several cancers including lung cancer." (PMID 22363346, 2012). "One candidate is FHIT at 3p14.2, which undergoes frequent hemizygous and occasional homozygous deletion in lung cancer cells and encodes a dinucleoside hydrolase." (PMID 15138482, 2004). "Owing to the connection between carcinogen exposure and Fhit loss, Fhit involvement in lung cancer was studied rather extensively early after discovery of the FHIT gene." (PMID 12771912, 2003). "The study suggests that targeting GSK3β could lead to new treatments for lung cancer with FHIT loss, offering hope for better therapies." (PMID 39762409, 2025). "Moreover, the combination of the two drugs did not further increase the synthetic lethality of VE-821 alone, suggesting that HRR inhibition plays a major role in the synthetic lethality in FHIT-deficient lung cancer cells." (PMID 39762409, 2025). "Another study found that the abnormal expression of FHIT may be associated with a variety of malignant tumors, such as lung cancer and breast cancer." (PMID 33732167, 2021). "Therefore, an assessment of HSP60/HSP10 levels (in association with the expression of FHIT) appears fundamental in choosing the kind of therapy to be used against lung cancer." (PMID 32318107, 2020). "Moreover, it was reported that high methylation levels of the p16, RASSF1A and FHIT genes were associated with significantly increased risk of lung cancer." (PMID 31483011, 2019). "FHIT promoter hypermethylation was positively linked to tumor staging, pathological grade, or lymph node metastasis of colorectal cancer, thyroid cancer and lung cancer." (PMID 29296239, 2017). "Lung cancer susceptibility in FHIT-deficient mice was increased by Vhl haploinsufficiency." (PMID 29296239, 2017). "The diagnostic role of FHIT gene in the lung cancer is relatively limited in the Caucasian population but may be useful in the Asians." (PMID 28036263, 2017). "Results indicate that paclitaxel-induced apoptosis enhanced by FHIT expression in lung cancer cells might be associated with modulation of Bcl-2-caspase signaling." (PMID 25880193, 2015).
lung carcinoma (continued). "Hypermethylation of FHIT gene promoter region was found more frequent in cancer tissue than that of NLT which may demonstrated association between lung cancer risk and FHIT gene promoter methylation." (PMID 24667261, 2014). "Loss of FHIT expression is observed in lung cancer and pre-neoplastic lesions." (PMID 23504373, 2013). "However, the diagnostic ability of the methylation status of the FHIT gene in lung cancer still remains unclear." (PMID 28036263, 2017). "Thus the diagnostic role of FHIT gene in the lung cancer may be relatively limited in the Caucasian population but useful in the Asians." (PMID 28036263, 2017). "Thus, FHIT (at 3p14.2), which undergoes frequent deletion in lung cancer cells and encodes a dinucleoside hydrolase, could be affected by LOH at D3S3697." (PMID 15138482, 2004). "In an attempt to exploit FHIT loss as a biomarker for the discovery of lung cancer targets, we conducted a synthetic lethal drug screen in FHIT-engineered lung cancer cell lines." (PMID 39762409, 2025). "To explore the underlying mechanism of the observed synthetic lethality induced by GSK3β inhibition, we first compared the basal expression levels of GSK3β in FHIT-expressing and FHIT-mutant lung cancer cell lines." (PMID 39762409, 2025). "We noted that FHIT loss activated both the HRR and NHEJ repair pathways in lung cancer cells and that the GSK3β inhibitor inhibited both pathways." (PMID 39762409, 2025). "We are currently investigating a genome-wide, FHIT-protein interaction analysis in lung cancer cells to uncover proteins and pathways that FHIT interacts with and modulates." (PMID 39762409, 2025). "To investigate the synthetic lethal targets of FHIT in lung cancer, we established FHIT-isogenic lung cancer cell pairs via CRISPR/Cas9 gene knockout (KO) and lentiviral FHIT overexpression (OE)." (PMID 39762409, 2025). "To evaluate the in vivo therapeutic effect of the GSK3β inhibitor on lung cancer with FHIT loss, we performed tumor xenograft experiments with parental and FHIT−/− HCC827 lung cancer cells in athymic nude mice." (PMID 39762409, 2025). "As a negative regulator of tumors, fragile histidine triad diadenosine triphosphatase (FHIT) can inhibit metastasis in lung cancer." (PMID 38361784, 2024). "For instance, the fragile histidine triad (FHIT) provides a new therapeutic target and strategy for the clinical treatment of lung cancer, which further enhances the therapeutic effect of lung cancer." (PMID 38074028, 2023). "In this LINC00173-SNAIL-FHIT axis, FHIT acts as a tumor suppressor to inhibit carcinogenesis and tumor progression in lung cancer." (PMID 38069335, 2023). "It is already known that genetic disruption of the FHIT gene, by means of allelic deletion, is found in large portion of lung cancer patients." (PMID 35663592, 2021). "In lung cancer, FHIT hypermethylation, which inactivated FHIT, was significantly higher in tumors than in normal lung tissues." (PMID 34368151, 2021). "Based on previous studies and our investigation, we believed that the methylation of 6 tumor suppressor genes (FHIT, p16, MGMT, RASSF1A, APC, and DAPK) was associated with the prognosis of lung cancer patients." (PMID 34257703, 2021). "Re-expression of FHIT in FHIT-negative highly invasive lung cancer cells inhibited migration and invasion, while FHIT knockdown in FHIT-positive poorly invasive cells increased their migratory or invasive potential." (PMID 34368151, 2021). "Aberrant transcripts of FHIT have been found in other kinds of tumors, such as gastric cancer, esophageal cancer, lung cancer, and colon carcinomas, indicating its potential role in suppressing carcinogenesis." (PMID 32375395, 2020). "Through this action on miR‐30c, FHIT counteracts the epithelial–mesenchymal transition (EMT) in human lung cancer cells." (PMID 31538680, 2020).
lung carcinoma (continued). "For FHIT:TSPAN8 gene pair identified from SQC cohort, individuals with genotype 0/1 had a significant reduced lung cancer risk with OR 0.63 and p value 9.15x10-6." (PMID 30956756, 2019). "We successfully identified epistasis in RGL1:RAD51B in ALL and NSCLC lung cancer, SYNE1:RNF43 in ADE and FHIT:TSPAN8 in SQC risk development." (PMID 30956756, 2019). "Three genes related to lung cancer were screened: Gremlin, fragile histidine triad (FHIT), and transcription factor 21 (TCF21)." (PMID 28811522, 2017). "FHIT induces autophagy and apoptosis in lung cancer cells, and suppresses the growth epithelial-mesenchymal transition (EMT) and metastasis." (PMID 29296239, 2017). "In this study, we performed a meta-analysis to evaluate the ability to use FHIT methylation level for early lung cancer diagnosis." (PMID 28036263, 2017). "Src family tyrosine kinases can phosphorylate FHIT at tyrosine 114 (Y114) within the unstructured loop C-terminal of the catalytic site, which induces Caspase- dependent apoptosis of lung cancer cells by decreasing survivin expression and Akt activity." (PMID 29296239, 2017). "Reportedly, FHIT expression was positively related to the favorable prognosis of the patients with lung cancer, oral squamous cell carcinoma, head and neck squamous cell carcinoma, diffuse large B-cell lymphoma and cervical cancer." (PMID 29296239, 2017). "FHIT delocalizes Annexin a4 from plasma membrane to cytosol and sensitizes lung cancer cells to paclitaxel." (PMID 29296239, 2017). "Studies showed reductions in the expression levels of FHIT have occurred in many kinds of malignancies, such as lung cancer, oropharyngeal squamous cell carcinomas, renal cell carcinomas and colorectal carcinomas." (PMID 28414756, 2017). "In this study, we demonstrate that elevated expression of FHIT leads to reduced motility and invasiveness of lung cancer cells in vitro and their ability to metastasize in vivo." (PMID 25340791, 2014). "Immunostaining for FHIT in lung cancer tissue revealed that FHIT expression was markedly reduced in metastatic tissue compared to non-metastatic (P = 0.03)." (PMID 25340791, 2014). "The odds ratio (OR) and range of FHIT gene of cancer tissue of lung cancer patients compared with normal lung tissue, plasma and the bronchial lavage fluid were pooled by statistical software Stata 11.0." (PMID 24667261, 2014). "Here it is shown that FHIT reduces the motility and invasiveness of lung cancer cells in vitro and ability to metastasize in vivo, at least partially through the miR-30c-mediated suppression of EMT, a critical process during tumor metastasis." (PMID 25340791, 2014). "Phosphatidylinositol 3-OH kinase (PI3K)-Akt-survivin is an important signaling pathway that was regulated by FHIT in lung cancer cells." (PMID 24757411, 2014). "FHIT (fragile histidine triad) is involved in various intracellular functions and a putative tumor suppressor for various cancers including lung cancer." (PMID 22952805, 2012). "The cloning of the fragile histidine triad(FHIT) gene at 3p14.2 in 1996 and the subsequent reports demonstrated frequent allelic deletion, aberrant FHIT transcripts in primary lung cancers, cell lines of small cell and nonsmall cell type." (PMID 12865924, 2003). "However, no actual targets or drugs targeting FHIT loss have been developed, despite the long-term investigation of FHIT in lung cancer." (PMID 39762409, 2025). "Olaparib, an inhibitor of PARP involved in DNA single-strand break repair, also did not have a significant synthetic lethal effect on FHIT-deficient lung cancer cells." (PMID 39762409, 2025). "In conclusion, this study revealed synthetic lethality between FHIT and GSK3β in lung cancer cells." (PMID 39762409, 2025). "Small molecule inhibitors of HRR, but not NHEJ or PARP, induced synthetic lethality in FHIT-deficient lung cancer cells." (PMID 39762409, 2025). "Researchers found a gap in targeting FHIT, a tumor suppressor gene often missing in lung cancer." (PMID 39762409, 2025).